CCDC51 (coiled-coil domain containing 51)
Description:
Pore-forming subunit of the mitochondrial ATP-gated potassium channel (mitoK(ATP)). Together with ATP-binding subunit ABCB8/MITOSUR of the mitoK(ATP) channel, mediates ATP-dependent K(+) currents across the mitochondrial inner membrane. An increase in ATP intracellular levels closes the channel, inhibiting K(+) transport, whereas a decrease in ATP levels enhances K(+) uptake in the mitochondrial matrix. May contribute to the homeostatic control of cellular metabolism under stress conditions by regulating the mitochondrial matrix volume.
Synonyms: MITOK; FLJ12436
Tractability: Antibody: UniProt predicts a signal peptide or a membrane-spanning region. PROTAC: ubiquitination databases record sites on it; its protein half-life has been measured.
Gene: Protein-coding gene on chromosome 3 (48,432,164 to 48,440,456, reverse strand). Ensembl gene ENSG00000164051.
Subcellular location: Mitochondrion inner membrane; Mitochondrion inner membrane (Isoform 1)
Subcellular location (Human Protein Atlas): Mitochondria; Nucleoplasm; Centrosome
Gene Ontology:
Molecular function: mitochondrial ATP-gated potassium channel activity; protein binding
Biological process: cell volume homeostasis; mitochondrial potassium ion transmembrane transport; potassium ion transmembrane transport
Cellular component: mitochondrial ATP-gated potassium channel complex; mitochondrial inner membrane; mitochondrion; nucleoplasm; potassium channel complex
Genetic constraint (gnomAD): Loss-of-function variants: 31 observed, 33.16 expected, observed/expected ratio (o/e) 0.93, 90% interval 0.7 to 1.26. The upper end of that interval is the gene's LOEUF score, 1.26, which puts it in group 5 of 6, group 1 being the genes least tolerant of losing a copy. Missense variants: 433 observed, 506.37 expected, observed/expected ratio (o/e) 0.86, 90% interval 0.79 to 0.93. Synonymous variants: 175 observed, 200.11 expected, observed/expected ratio (o/e) 0.87, 90% interval 0.77 to 0.99.
Homologues: Orthologues: chimpanzee CCDC51 (99% identical), macaque CCDC51 (97% identical), dog CCDC51 (88% identical), rabbit CCDC51 (88% identical), pig CCDC51 (86% identical), guinea pig CCDC51 (83% identical), rat Ccdc51 (82% identical), mouse Ccdc51 (81% identical).
Diseases named in the same sentence as CCDC51 in open-access papers:
CCDC51 is named in the same sentence as 18 diseases in open-access papers, as found by Europe PMC text mining. Sharing a sentence is not in itself a finding about the gene and the disease. The quoted sentences say what the papers report.
ischemia (1 paper, 2025). A hypoperfusion of the BLOOD through an organ or tissue caused by a PATHOLOGIC CONSTRICTION or obstruction of its BLOOD VESSELS, or an absence of BLOOD CIRCULATION. "Thus, while cellular stress such as ischemia may induce mitochondrial K+ influx via a CCDC51/ABCB8 channel, we propose this is counterbalanced by a ROMK2/SUR2A-55 channel promoting K+ efflux." (PMID 40332433, 2025).
osteonecrosis (1 paper, 2019). A none disease characterized by death of bone tissue due to a lack of blood supply. "Mouse Ccdc51 gene is the target gene of miR-672-5p, which is highly expressed after steroid-induced osteonecrosis." (PMID 31097004, 2019).
cancer (6 papers, 2020 to 2025). A tumor composed of atypical neoplastic, often pleomorphic cells that invade other tissues. "By influencing redox balance and maintaining mitochondrial structure, CCDC51 plays a key role in managing how cancer cells survive and adapt to stress, highlighting its potential as a therapeutic target in cancer treatment." (PMID 38396807, 2024). "The study’s findings that CCDC51 is essential for mitochondrial response to cellular stress have important implications in cancer cell biology." (PMID 38396807, 2024).
infection (2 papers, 2024 to 2025). The state of being infected such as from the introduction of a foreign agent such as serum, vaccine, antigenic substance or organism. "In our study, the IHC targeting CCDC51 (MitoKATP) revealed upregulation during intranasal infection with SARS-CoV-2 variants." (PMID 40004042, 2025).
tumours (1 paper, 2017). "The most common 44 genes (p<0.001) including VHL enlist MON1A, CCDC51 and TMA7 at 3p21.31 (31/29 HRO tumours), and MIRLET7G and WDR28 at 3p21.1 (31/31 tumours), respectively." (PMID 28486536, 2017).
CCDC51 also shares sentences with these, for which no sentence is quoted: pancreatic ductal adenocarcinoma (3 papers); atrial fibrillation (1); Autosomal Recessive Rod-Cone Dystrophy (1); behavioral disorders (1); brain tumors (1); cardiac disease (1); COVID-19 (1); Fanconi anemia (1); hypertrophic cardiomyopathy (1); hypothyroidism (1); melanoma (1); nephrolithiasis (1); Parkinson disease (1).